EPOR (erythropoietin receptor)
Diseases named in the same sentence as EPOR in open-access papers (continued):
Sharing a sentence is not in itself a finding about the gene and the disease.
anemia (continued). "A specific role for endogenous EPO in cardiovascular development was provided by mice lacking EPO or EPOR that exhibit developmental angiogenic and cardiac defects including ventricular hyperplasia prior to death in utero due to severe anemia." (PMID 38628440, 2024). "The beneficial effect of canagliflozin on anemia was consistent across patients with and without anti-EPOR antibodies." (PMID 38344715, 2024). "EPO−/− and EPOR−/− mice die in utero at E13.5 due to lack of definitive erythropoiesis and the resultant severe anemia." (PMID 34603036, 2021). "Improving anemia and targeting CD163+EPOR+ TAMs may serve as potential therapeutic interventions in osteosarcoma lung metastasis." (PMID 32908942, 2020). "Because most osteosarcoma patients have anemia, which can induce high levels of EPO and TAMs in osteosarcomas express EPOR, verify that EPO plays a role in the protumor function of TAMs, we cultured primary TAMs collected from patients with osteosarcoma lung metastases using CD14 microbeads." (PMID 32908942, 2020). "Some researchers have revealed that Herba Leonuri obviously increased the numbers of erythrocyte, attenuated the levels of EPOR and IL6, inhibited HIF-1α expression, and consequently improved the anemia, which supported its crucial role in the improvement of anemia." (PMID 29551975, 2018). "Finally, in the context of tumor hypoxia, the wide use of rhEPO to treat anaemia in cancer patients, especially ccRCC, is still being discussed because of HIF-induced EPO and EPOR overexpression." (PMID 26210994, 2015). "Both the embryonic deletion of Gfi1b by EpoR-Cre and the deletion in adult mice by Mx-Cre or Cre-ERT leads to reduced numbers of erythroid precursors, perturbed and delayed erythroid maturation, anemia and extramedullary erythropoiesis." (PMID 24800817, 2014). "Anaemia therapies include red blood cell (RBC) transfusions and erythropoiesis-stimulating agents (ESAs), which increase RBC production in bone marrow by activating the erythropoietin receptor (EpoR) on erythrocytic-progenitor cells." (PMID 22395661, 2012). "On the other hand, EPOR is highly expressed in the developing mouse brain, and mice lacking EPO or EPOR experienced increased apoptosis in the brain before they died of severe anemia in the uterus." (PMID 22216265, 2011). "Alternative mRNA splicing produces a soluble form of EpoR (sEpoR) found in human blood, however its role in anemia is not known." (PMID 20169072, 2010). "Mice lacking EPO or its receptor (EPOR) die in utero due to severe anemia." (PMID 39996752, 2025). "Mice lacking EPO or EPOR die mid-gestation due to severe anemia." (PMID 39996752, 2025). "Thus, we speculated that combined analyses of anemia and the percentage of CD163+EPOR+ TAMs may better predict the prognosis of osteosarcoma lung metastasis patients." (PMID 32908942, 2020). "While the question remains about how a low level of EpoR can provide a direct EPO response, various responses to EPO observed in animal and cell models of ischemic stress, injury or metabolism in non-hematopoietic tissues suggest therapeutic benefit for EPO beyond anemia." (PMID 24918289, 2014). "Mice lacking Stat5 die perinatally of severe anemia,suggesting that the functions of Stat5 in erythropoiesis are essential to life.By contrast, EpoR-HM mice, which retain only the binary low-intensity p-Stat5signal, are viable and have near-normal basal erythropoiesis." (PMID 22969412, 2012). "Unlike mice that lack either EPO or EpoR resulting in death in utero, double knockout of both STAT5A and STAT5B is not embryonic lethal and, rather, results in fetal anemia and defective response in adult mice to erythroid stress." (PMID 24918289, 2014). "In line with the results from the REACH3 trial, the most common adverse event was anemia, which is not surprising taking into account the mechanism of action with JAK inhibition interfering with erythropoietin receptor signaling and the reported safety profile of ruxolitinib." (PMID 38916742, 2024).
anemia (continued). "Targeted deletion in mice of either EPO or EpoR leads to a marked decrease in circulating primitive erythroblasts in utero by day E11.5, and definitive erythroid progenitor cells at the CFU-E (colony forming unit-erythroid) stage do not survive resulting in severe anemia and death at day E13.5." (PMID 22567318, 2012).
erythrocytosis (36 papers, 2006 to 2025). "The two patients were young women with simple polycythemia and clear family history, and identified to carry the truncated mutation c.1316G>A(p.W439*)of EPOR gene." (PMID 41407468, 2025). "Primary familial and congenital polycythemia (PFCP) is a rare autosomal-dominant disorder characterized by congenital erythrocytosis, where mutations in the erythropoietin receptor (EpoR) have been identified." (PMID 40507313, 2025). "While germline EPOR mutations can result in autosomal-dominant benign erythrocytosis, truncated EPOR proteins activate JAK-STAT signaling." (PMID 39941315, 2025). "A notable example is the G6002A mutation in the erythropoietin receptor (EPOR) gene, associated with erythrocytosis, a condition characterized by increased RBC production." (PMID 39684752, 2024). "The two factors that appeared to predict the detection of a reportable variant were low EPO (for PV and EPOR mutation) and a positive family history (for familial erythrocytosis)." (PMID 39335122, 2024). "Structurally abnormal EPOR genes have been identified in patients with primary familial and congenital polycythemia, suggesting a possible connection between EPOR mutations and erythrocytosis." (PMID 39590603, 2024). "We analyzed the presence of EPOR variants in two patients with polycythemia in whom JAK2 pathogenic variants had been previously discarded." (PMID 36292571, 2022). "The sporadic primary hereditary erythrocytosis is caused mainly by the erythropoietin receptor gene (EpoR) mutation." (PMID 34899081, 2021). "The polycythemia mouse model with JAK2 V617F mutation in hematopoietic cells gives rise to constitutively active EPOR, low EPO concentrations in the serum, low trabecular bone volume, and reduced osteoblast number." (PMID 33330462, 2020). "One patient who experienced polycythemia with a family history and germline EPOR mutation was also excluded." (PMID 35847744, 2020). "(Note: In polycythemia patients harboring truncated EPOR forms, a normal wild-type EPOR allele typically is also expressed)." (PMID 22253704, 2012). "(Notably, truncated EPOR alleles typically are co-expressed together with a normal EPOR allele in primary familial and congenital polycythemia patients)." (PMID 22253704, 2012). "Based on overall findings, a model is outlined in which multiple mechanisms are suggested to contribute to gain-of-function properties of polycythemia-associated C-terminally truncated, EPOR mutant alleles." (PMID 22253704, 2012). "Overall, the present studies provide new insight into EPOR expression dynamics, as well as complex mechanisms via which mutated EPOR alleles can contribute to polycythemia." (PMID 22253704, 2012). "Beyond this, when C-terminal truncated hEPOR-T mutant alleles as harbored by polycythemia patients are co-expressed with the wild-type EPOR in EPO-dependent erythroid progenitors, several specific events become altered." (PMID 22253704, 2012). "With the erythropoietin receptor (EpoR) for example, a truncated receptor with loss of the cytoplasmic carboxyl terminal leads to familial polycythemia." (PMID 17032464, 2006). "To discover genetic variants in unexplained erythrocytosis, we performed whole exome sequencing in 27 patients with JAK2-negative polycythemia after excluding the presence of any mutations in genes previously associated with erythrocytosis (EPOR, VHL, PHD2, EPAS1, HBA, and HBB)." (PMID 37428608, 2023). "Primary familial and congenital polycythemia is a rare disease characterized by an increase in red cell mass that may be due to pathogenic variants in the EPO receptor (EPOR) gene." (PMID 36292571, 2022). "Nevertheless, increased EpoR expression in BM cells may be associated with erythrocytosis because EpoR is required to suppress apoptosis in later stages of erythroblast maturation." (PMID 33481887, 2021).
erythrocytosis (continued). "Because controversy exists regarding the specificity of antibodies to EPOR11,12, we used unique humanized knock-in mice that either express the human EPOR gene (hWtEPOR) or a mutant truncated human EPOR gene (hMtEPOR) known to cause human polycythemia in place of the murine EPOR gene (mWtEPOR)." (PMID 29391474, 2018). "These familial erythrocytosis cases are caused by mutations in genes such as VHL, EPAS, ELGN1 and EPOR." (PMID 39335122, 2024). "Previous study illustrated therapeutic potential of blocking EPO/EPOR/JAK/STAT signaling in HCC patients with polycythemia." (PMID 35837663, 2022). "The polycythemia JAK2V617F mouse model with constitutively active EPOR has reduced bone and normal osteoclast numbers." (PMID 33330462, 2020). "A well-characterized example is congenital erythrocytosis—the non-pathogenic hyper-production of red blood cells—that is caused by a truncated erythropoietin receptor." (PMID 38886504, 2024). "Of the four remaining genes, human disease is already associated with variants in PLEKHM1 (OMIM #611497 osteopetrosis) and EPOR (OMIM #133100 erythrocytosis), but the family presented here does not exhibit either of these phenotypes." (PMID 32167558, 2020). "We present a long-term survey of pediatric liver recipients, evaluating prevalence, outcome and the main potential causes of erythrocytosis, including a comprehensive mutational analysis of commonly related genes (mutations of HBB and HBA, JAK2, EPOR, VHL, EPAS1 and EGLN1)." (PMID 32546701, 2020). "Secondary polycythemia occurs as a consequence of elevated circulating erythropoietin (EPO), while primary polycythemia is due to intrinsic factors (e.g., somatic JAK2V617F mutation and hereditary dominant EPOR mutations) of erythroid progenitors in the bone marrow and is EPO-independent." (PMID 31091718, 2019). "SFFV-A, which encodes an envelope protein that cannot activate the EpoR, still causes Epo-independent erythroid cell hyperplasia in mice, although the animals do not develop polycythemia." (PMID 21994618, 2010). "SFFV Env can also interact with the EpoR, but this interaction drives Epo-independent differentiation, causing polycythemia, and does not appear to be essential for the development of erythroid hyperplasia." (PMID 21994618, 2010). "Consequently, these aspects of EPOR biology are not well defined, nor are actions of polycythemia- associated mutated EPOR alleles." (PMID 22253704, 2012). "To evaluate the atherogenic role of VFEpoR RBCs in a model that mimics human polycythemia, we injected the same low-dose EPO into hyperlipidemic littermate EpoR-Cre control and VFEpoR mice that were fed the WD for 12 weeks." (PMID 35587375, 2022). "In rare instances, SH2B3/LNK exon 2 mutations or polymorphisms have been reported in patients with unexplained erythrocytosis, with subnormal serum EPO levels, and absence of JAK2, MPL, and EPOR mutations." (PMID 34021251, 2021). "In the patient with the mutation in PHD1 (EGLN2), sensitivity of erythroid progenitors to EPO and erythropoietin receptor (EpoR) activity were inappropriately increased and resulted in polycythemia with no or mild increase in EPO levels with increased EpoR expression." (PMID 30538672, 2018). "Thus, interaction of SFFV-P Env with the EpoR appears to be responsible for the development of Epo-independent erythroid differentiation and polycythemia and not required for the development of SFFV-induced erythroid cell hyperplasia." (PMID 21994618, 2010). "Furthermore, mice in which the mouse EpoR has been replaced with the human EpoR, which cannot be activated by SFFV Env, still develop SFFV-P-induced erythroblastosis but not polycythemia." (PMID 21994618, 2010).
breast carcinoma (28 papers, 2007 to 2026). "Hypoxia is associated with the induction of EPO and EPOR mRNA expression along with their related proteins in breast carcinomas." (PMID 29108271, 2017). "EPOR overexpression in tumor tissue is associated with a poor prognosis in a variety of malignancies, including breast cancer, melanoma, renal cell carcinoma, gastric cancer, pediatric tumors, and uterine and ovarian carcinoma." (PMID 22639817, 2012). "Moreover, the loss of EPOR delays in vitro breast cancer cell growth as well as in vivo tumor growth in breast cancer and glioma models." (PMID 36052260, 2022). "In this study, we describe erythropoietin (EPO) and erythropoietin receptor (EPOR) as novel targets of miR-125b and we tested the hypothesis of an association between miRNA/targets expression and clinical outcomes in breast cancer." (PMID 24165569, 2013). "A notable increase in cell viability was observed in both HT-29 and COLO 320DM cells 24 h after transfection, which goes against the assumptions derived from studies in other cancer models where EPOR silencing affects viability, such as breast cancer." (PMID 41514679, 2026). "In our previous studies, overexpression of EPOR in RAMA 37-28 breast cancer cells altered the sensitivity of these cells to tamoxifen and paclitaxel via mechanism related to prolonged activation of AKT and ERK1/2 pathways, respectively." (PMID 37239828, 2023). "The co-inhibition of iNOS and AKT reduced mitochondrial density and TFAM in additional lung and breast cancer cell lines, suggesting that other cancer cells also rely on the regulation of mitochondrial biogenesis by iNOS and pAKT downstream of EPOR." (PMID 36052260, 2022). "Other authors have shown that the EPO/EPOR axis plays an important role in the regulation of the migration and invasion of breast cancer cells." (PMID 28430808, 2017). "In a xenotransplantation model, designed to simulate recombinant EPO therapy in breast cancer patients, knockdown of EPOR markedly reduced tumor growth." (PMID 28418910, 2017). "Here we have examined the impact of EPOR modulation in breast cancer cell lines and in a xenotransplantation model designed to simulate EPO treatment in cancer patients." (PMID 28418910, 2017). "In contrast, recurrence-free survival was significantly improved in patients with ER(+) tumors with high EPOR expression in the untreated cohort, implying that EPOR expression in breast cancer affects tumor behavior." (PMID 28418910, 2017). "Given that EPO-induced signalling components are more readily detected in the Rama 37 cells overexpressing EPOR, the results of the two studies are in good agreement and corroborate the idea that the EPO-EPOR axis is important in breast cancer progression." (PMID 28418910, 2017). "Cell-surface expression of EpoR, as well as total EpoR (assessed in breast cancer sample cohort) was also analyzed using specific EpoR monoclonal antibodies." (PMID 25807104, 2015). "This included evaluation of receptor function and protein expression in freshly-derived human breast tumor tissues, including both Her2+ and Her2- tumors to address specific questions related to the biological relevance EpoR in breast cancer." (PMID 25807104, 2015). "As one example, MCF-7 breast-cancer cells have a total of only 100 EpoR dimers/cell vs the ∼10,000 receptors (surface plus cytoplasmic EpoR) seen in erythroid progenitors but have been reported to respond to Epo addition." (PMID 24337485, 2014). "Among them, we validated erythropoietin (EPO) and its receptor (EPOR) - frequently overexpressed in breast cancer - as true targets of miR-125b." (PMID 24165569, 2013). "In contrast, EpoR protein was reportedly detectable in a breast tumor cell line (MCF-7) and breast cancer tissues with an anti-EpoR polyclonal antibody (M-20), and functional responses to rHuEpo were reported with MCF-7 cells." (PMID 23861852, 2013).
breast carcinoma (continued). "In other studies the anti-EpoR polyclonal antibody M-20, which is a polyclonal antibody raised to a murine EpoR peptide and thought to show some specificity to human EpoR, was used to examine EpoR protein expression in breast cancer samples." (PMID 23861852, 2013). "We validated the opposite modulation of miR-125b, EPO and EPOR by RT-qPCR in a cohort of 42 breast cancer patients and 13 normal samples collected at the University of Ferrara." (PMID 24165569, 2013). "The objective of our study was to investigate the effect of rHuEPO on cell proliferation, EPOR expression and early gene response in breast cancer cells." (PMID 24294184, 2013). "Erythropoietin (EPO) and its receptor (EPOR) were validated as targets of miR-125b by luciferase assay and their expression was assessed by RT-qPCR in 42 breast cancers and 13 normal samples." (PMID 24165569, 2013). "The expression profile of EPOR and EPOR-T was determined in a range of breast cancer cell lines and compared with their invasive properties." (PMID 24294184, 2013). "In this work, we confirmed the down-regulation of miR-125b and the up-regulation of EPO and EPOR in a large panel of breast cancers." (PMID 24165569, 2013). "In this study, we investigated the effect of human recombinant erythropoietin (rHuEPO) on cell proliferation, early gene response and the expression of EPOR isoforms in the MCF-7 breast cancer cell line." (PMID 24294184, 2013). "Coexpression of EpoR and endogenous Epo has been detected in a variety of primary cancers and tumor cell lines, including non-small cell lung cancer, breast cancer, and cervical cancer." (PMID 22188703, 2011). "We evaluated the activation of EPO-dependent signal transduction in R3230 mammary carcinoma cells engineered to express the constitutively active EPOR-R129C mutant." (PMID 17579721, 2007). "Several reports have suggested that EPO and EPO stimulating agents could promote tumor cell proliferation through its specific receptor (EPOR) and hypoxia in head and neck tumors, breast cancer and HCC." (PMID 36961524, 2023). "EPOR is present not only in hematopoietic cells but also in non-hematopoietic cells such as neurons, endothelial cells, and skeletal muscle cells and in various tumors such as breast cancer and head and neck cancer." (PMID 35359375, 2022). "Moreover, exposure of HER2 and EPOR dual-positive breast cancer cell lines to trastuzumab inhibited AKT and ERK phosphorylation, but the inhibition was reduced by simultaneous treatment with recombinant EPO." (PMID 28418910, 2017). "Moreover, EPO/EPOR promoted tumorigenesis in genetically engineered mouse models of breast cancer by activating JAK/STAT signaling in breast tumor-initiating cells (TICs) and promoted its self-renewal." (PMID 25426117, 2014). "Additionally, the expression profile of EPOR and EPOR-T was determined in a range of breast cancer cell lines and compared with their invasive properties." (PMID 24294184, 2013). "Indeed, both EPO and EPOR 3′UTRs have at least one target sequence for miR-125b that responded to a miR-125b mimic transfection in the context of breast cancer cells." (PMID 24165569, 2013). "Conversely, targeting endogenous EPO using recombinant soluble EPOR (sEPOR) or a neutralizing anti-EPO monoclonal antibody co-injected into window chambers with mammary carcinoma cells inhibits the initiation of tumor angiogenesis and delays growth during the initial stages of tumorigenesis." (PMID 17579721, 2007). "Similarly, high expression of EPO and its receptor, EPOR, has recently been described in breast cancer cells, and in regions of hypoxia in breast tumors, suggesting that this gene may be involved in breast tumorigenesis by promoting tissue hypoxia." (PMID 27708222, 2016).